ABCF3 (ATP binding cassette subfamily F member 3)
Description:
Displays an antiviral effect against flaviviruses such as west Nile virus (WNV) in the presence of OAS1B.
Synonyms: EST201864
Tractability: PROTAC: ubiquitination databases record sites on it; its protein half-life has been measured.
Gene: Protein-coding gene on chromosome 3 (184,186,095 to 184,194,013, forward strand). Ensembl gene ENSG00000161204.
Subcellular location (Human Protein Atlas): Cytosol; Nucleoli
Gene Ontology:
Molecular function: cadherin binding; protein binding; ATP binding; ATP hydrolysis activity
Cellular component: membrane
Genetic constraint (gnomAD): Loss-of-function variants: 62 observed, 98.66 expected, observed/expected ratio (o/e) 0.63, 90% interval 0.51 to 0.78. The upper end of that interval is the gene's LOEUF score, 0.78, which puts it in group 3 of 6, group 1 being the genes least tolerant of losing a copy. Missense variants: 843 observed, 961.24 expected, observed/expected ratio (o/e) 0.88, 90% interval 0.83 to 0.93. Synonymous variants: 355 observed, 374.99 expected, observed/expected ratio (o/e) 0.95, 90% interval 0.87 to 1.03.
Homologues: Orthologues: chimpanzee ABCF3 (99% identical), pig ABCF3 (98% identical), rabbit ABCF3 (98% identical), mouse Abcf3 (97% identical), guinea pig ABCF3 (97% identical), rat Abcf3 (95% identical), dog ABCF3 (94% identical), macaque ABCF3 (94% identical), tropical clawed frog abcf3 (77% identical), Drosophila melanogaster CG9330 (56% identical), Caenorhabditis elegans abcf-3 (51% identical), zebrafish abcf3 (26% identical). Paralogues in human: ABCF1 (40% identical), ABCF2 (33% identical).
Diseases named in the same sentence as ABCF3 in open-access papers:
ABCF3 is named in the same sentence as 8 diseases in open-access papers, as found by Europe PMC text mining. Sharing a sentence is not in itself a finding about the gene and the disease. The quoted sentences say what the papers report.
dementia (1 paper, 2023). Loss of intellectual abilities interfering with an individual's social and occupational functions. "Additionally, downregulation of ABCF3 has been associated with an increase in viral load after infection by a flavivirus, specifically the West Nile virus which has been linked to long-term neurological problems and dementia." (PMID 37198259, 2023).
ovarian carcinoma (1 paper, 2023). A malignant neoplasm originating from the surface ovarian epithelium. "Similarly, the MAP-defined antigens ABCF3 and ANXA2 were also highly expressed across healthy tissues, while CRABP2, although significantly over-expressed in ovarian cancer samples, was expressed at similar or greater levels in several healthy sites." (PMID 36943460, 2023).
viral infection (1 paper, 2023). "It’s plausible that in the presence of viral infection, changes in ABCF3 expression may affect immune response and inflammation, two processes that play a role in the amyloid cascade hypothesis." (PMID 37198259, 2023).
cancer (3 papers, 2014 to 2025). A tumor composed of atypical neoplastic, often pleomorphic cells that invade other tissues. "Each gene in this network (gcn-1, abcf-3, sptf-3, pig-1, egl-1, ceh-34 and eya-1) has a human counterpart, some of which are implicated in human diseases, including developmental disorders and cancer." (PMID 25101958, 2014). "ABCD3 is a fatty acid-CoA transporter and the ABCF3 protein is a lipid transporter, both of which do not transport cancer drugs." (PMID 40723843, 2025).
infection (3 papers, 2020 to 2023). The state of being infected such as from the introduction of a foreign agent such as serum, vaccine, antigenic substance or organism. "It has been demonstrated that ABCF3 is also involved in the control of protein translation, defense against pathogen infection, and regulation of H2O2 uptake by modulating the expression of aquaporin genes." (PMID 34961078, 2021). "Only 3 (ABCF3, CNEP1R1, TWF1) out of 11 genes shared between moDC and cDC2 were up-regulated in response to infection." (PMID 33365028, 2020).
tumor (1 paper, 2021). "Moreover, a number of pathogenic mutations, such as in ABCF3, were detected in both, U-CH11 and U-CH11R, but not in the tumor tissue." (PMID 34330313, 2021).
ABCF3 also shares sentences with these, for which no sentence is quoted: breast carcinoma (1 paper); lung carcinoma (1).